LIAS (lipoic acid synthetase)
Description:
Catalyzes the radical-mediated insertion of two sulfur atoms into the C-6 and C-8 positions of the octanoyl moiety bound to the lipoyl domains of lipoate-dependent enzymes, thereby converting the octanoylated domains into lipoylated derivatives.
Synonyms: LS; LAS; HUSSY-01; HGCLAS; LIP1; PDHLD
Tractability: PROTAC: its protein half-life has been measured.
Gene: Protein-coding gene on chromosome 4 (39,459,004 to 39,485,109, forward strand). Ensembl gene ENSG00000121897.
Subcellular location: Mitochondrion
Subcellular location (Human Protein Atlas): Nucleoplasm; Mitochondria
Pathways (Reactome):
Metabolism of proteins: Protein lipoylation
Gene Ontology:
Molecular function: lipoate synthase activity; 4 iron, 4 sulfur cluster binding; catalytic activity; iron-sulfur cluster binding; sulfurtransferase activity
Biological process: inflammatory response; lipoate biosynthetic process; response to lipopolysaccharide; response to oxidative stress; protein lipoylation
Cellular component: mitochondrion; mitochondrial matrix
Genetic constraint (gnomAD): Loss-of-function variants: 27 observed, 37.7 expected, observed/expected ratio (o/e) 0.72, 90% interval 0.53 to 0.99. The upper end of that interval is the gene's LOEUF score, 0.99, which puts it in group 4 of 6, group 1 being the genes least tolerant of losing a copy. Missense variants: 331 observed, 367.46 expected, observed/expected ratio (o/e) 0.9, 90% interval 0.82 to 0.99. Synonymous variants: 121 observed, 125.03 expected, observed/expected ratio (o/e) 0.97, 90% interval 0.83 to 1.12.
Gene-disease validity (ClinGen):
ClinGen rates the evidence that LIAS causes each of these diseases.
mitochondrial disease (autosomal recessive): Moderate.
Leigh syndrome (autosomal recessive): Limited. A progressive neurological disease defined by specific neuropathological features associating brainstem and basal ganglia lesions.
Homologues: Orthologues: chimpanzee LIAS (99% identical), macaque LIAS (99% identical), rabbit LIAS (96% identical), dog LIAS (94% identical), guinea pig LIAS (94% identical), pig LIAS (94% identical), rat Lias (91% identical), mouse Lias (90% identical), tropical clawed frog lias (82% identical), zebrafish lias (76% identical), Drosophila melanogaster Las (62% identical), Caenorhabditis elegans lias-1 (54% identical).
Diseases named in the same sentence as LIAS in open-access papers:
LIAS is named in the same sentence as 88 diseases in open-access papers, as found by Europe PMC text mining. Sharing a sentence is not in itself a finding about the gene and the disease. The quoted sentences say what the papers report.
breast carcinoma (10 papers, 2022 to 2026). "Furthermore, pan-cancer analysis of copper death-related genes indicated that LIAS mutations are associated with poorer survival outcomes in certain cancers, such as breast cancer." (PMID 40265013, 2025). "LIAS mutations impairs mitochondrial energy metabolism Moreover, high LIAS expression has been documented to be related to a favorable prognosis in patients with KIRC, rectal adenocarcinoma (READ), breast carcinoma, and ovarian carcinoma." (PMID 40367233, 2025). "We found that a high LIAS expression was related to the good prognosis in patients with kidney renal clear cell carcinoma (KIRC), rectum adenocarcinoma (READ), breast cancer, and ovarian cancer." (PMID 35982953, 2022). "FDX1 (P < 1E‐12), LIAS (P = 2.22E‐16), LIPT1 (P < 1E‐12), DLD (P < 5.46E‐09), DLAT (P = 3.14E‐02), PDHA1 (P = 1.15E‐07), MTF1 (P = 1.07E‐09), and GLS (P = 2.48E‐05) were downregulated in breast cancer, while PDHB (P = 5.04E‐07) and CDKN2A (P = 1.62E‐12) were upregulated." (PMID 39432636, 2024). "As cuproptosis-promoting genes, FDX1, LIAS, LIPT1, DLD, DLAT, and PDHA1 were under-expressed in breast cancer; at the same time, CDKN2A, which inhibited cuproptosis, was over-expressed in breast cancer, suggesting that cuproptosis might involve in the protective mechanism of BRCA." (PMID 39432636, 2024).
ovarian carcinoma (6 papers, 2022 to 2025). A malignant neoplasm originating from the surface ovarian epithelium. "The high expression of LIAS is associated with poor prognosis in lung cancer, whereas in KIRC and ovarian cancer, high expression of LIAS indicates better prognosis." (PMID 39309446, 2024). "In this study, the expression of LIAS in ovarian cancer was downregulated significantly, and the prognostic analysis suggested that LIAS is a protective gene." (PMID 36307842, 2022). "Kaplan-Meier plotter analysis showed that except for LIAS, PDHB, and ATP7B, the factors related to PDHB were significantly negatively correlated with the survival cycle of ovarian cancer patients." (PMID 36484005, 2022). "Furthermore, it was found that inhibiting LRPPRC expression not only diminishes the translation of the core subunit MTCO1 of complex IV and the copper chaperone molecule SCO1 in A2780 and SKOV3 ovarian cancer cells, but also reduces the expression levels of FDX1 and LIAS." (PMID 41516324, 2025).
lung carcinoma (5 papers, 2022 to 2024). "High expression of LIAS was associated with good prognosis in patients with ccRCC, READ, BRCA, and OC, whereas high expression of LIAS was associated with poor prognosis in lung cancer patients." (PMID 39482784, 2024). "By systematically analyzing the genetic alterations of 10 cuproptosis-related genes in lung adenocarcinoma, we found that CDKN2A, DLAT, LIAS, PDHA1, FDX1, GLS, and MTF1 were differentially expressed between lung cancer tissues and adjacent tissues." (PMID 36712848, 2022). "In addition, TNMplot indicated the similar transcriptional changes of LIAS in KIRC, OV, and lung cancers." (PMID 35982953, 2022).
melanoma (5 papers, 2022 to 2023). A malignant, usually aggressive tumor composed of atypical, neoplastic melanocytes. "Moreover, in melanoma patients treated with the CTLA4 inhibitor, LIAS expression was negatively linked with infiltration of CTL." (PMID 35982953, 2022). "We found that the expression of FDX1, LIAS, LIPT1, DLD, DLAT, MTF1, and CDKN2A were significantly lower in melanoma than in normal tissues." (PMID 36824136, 2023). "Moreover, in melanoma patients treated with the CTLA4 inhibitor, LIAS expression was negatively correlated with infiltration of CTL (r = -6.05e-01, p = 1.69e-02)." (PMID 35982953, 2022). "CRGs with low and moderate CNV, such as PDHA1, DLAT, GLS, and LIAS, were overexpressed in CRC comparison to those in normal melanoma samples, whereas CRGs with high CNV, such as PDHB, were significantly increased in melanoma samples, implying that CNV may regulate CRG mRNA expression." (PMID 36824136, 2023). "In addition, previous studies revealed that high expression of LIAS and LIPT1 were favorable for the prognosis of clear cell renal cell carcinoma, and LIPT1 could also be considered as an indicator of favorable prognosis in melanoma." (PMID 36276092, 2022).
glioma (4 papers, 2022 to 2023). A benign or malignant brain and spinal cord tumor that arises from glial cells (astrocytes, oligodendrocytes, ependymal cells). "In glioma patients, the levels of CDKN2A, FDX1, DLD, DLAT, LIAS, LIPT1, and PDHA1 were significantly associated with the OS, disease-specific survival, and progression-free interval." (PMID 36579333, 2022). "Furthermore, Cox regression analysis in the TCGA database showed that FDX1, LIPT1, DLD, DLAT, SLC31A1, ATP7A, and DLST might be risk factors; however, LIAS, ATP7B, and GCSH were significant preventive factors for gliomas." (PMID 37515314, 2023).
lactic acidosis (4 papers, 2015 to 2025). Metabolic acidosis characterized by the accumulation of lactate in the body. "Loss of lipoic acid synthase (LIAS) contributes to PDHC lipoic acid synthetase deficiency (PDHLD, MIM #614462), characterized by lactic acidosis, hyperglycaemia, delayed psychomotor development and seizures." (PMID 36475414, 2022). "In line with this, mice deficient in lipoic acid synthase undergo early embryonic lethality, and pathogenic variants identified in the human lipoic acid synthase (LIAS) are the cause of severe metabolic crisis accompanied by hyperglycinemia, lactic acidosis, and seizures." (PMID 32481479, 2020).
cholangiocarcinoma (3 papers, 2022 to 2025). A carcinoma that arises from the intrahepatic biliary tree (intrahepatic cholangiocarcinoma) or from the junction, or adjacent to the junction, of the right and left hepatic ducts (hilar cholangiocarcinoma). "Some studies showed that LIAS expression is upregulated in lung adenocarcinoma, hepatocellular carcinoma, cholangiocarcinoma, and other tumors." (PMID 40265013, 2025). "We found that the LIAS expression was upregulated in some cancers, such as cholangiocarcinoma (CHOL), liver hepatocellular carcinoma (LIHC), LUAD, and lung squamous cell carcinoma (LUSC)." (PMID 35982953, 2022). "Most copper induced cell death genes were downregulated in various cancers, such as FDX1 in cholangiocarcinoma (CHOL); LIAS and LIPT1 in bladder cancer (BLCA); PDHB in glioblastoma (GBM) and kidney chromophobe cancer (KICH)." (PMID 36581992, 2022).
brain cancer (2 papers, 2022). A primary or metastatic malignant neoplasm affecting the brain. "Brain cancers (GBM and LGG) were found to potentially have a higher copper metabolism-related cell death compared to normal brain tissue because their anti-cuproptosis gene ATP7B was downregulated with pro-cuproptosis genes SLC31A1, FDX1, DLAT, and LIAS upregulated in cancer tissues." (PMID 36276096, 2022).
celiac disease (2 papers, 2022 to 2024). An autoimmune genetic disorder with an unknown pattern of inheritance that primarily affects the digestive tract. "Cuproptosis-related regulators exhibited extensive differential expression in Crohn’s Disease (CD), Ulcerative Colitis (UC), Celiac Disease (CEL), and IBD-induced cancer (IBD-CA) that share common differential genes (PDHA1, DBT, DLAT, LIAS)." (PMID 36405733, 2022).
clear cell renal cell carcinoma (2 papers, 2022). "The results demonstrated that ATP7B, DLAT, and LIAS were upregulated in the 786-O cell line, which represented human renal clear cell adenocarcinoma cell, compared to the HK-2 cell line; while DBT and PDHB were found to be downregulated in 786-O cells." (PMID 36092880, 2022).
colitis (2 papers, 2022 to 2025). Inflammation of the colon. "Our study is the first to demonstrate the accumulation of copper in the colonic mucosa, resulting in the loss of Fe-S cluster-containing proteins FDX1 and LIAS and a reduction in DLAT oligomerization leading to cuproptosis in DSS-induced colitis mice." (PMID 40969742, 2025). "PA inhibited cuproptosis in the intestinal barrier of mice with colitis by reducing excess copper levels and DLAT oligomerization, as well as rescuing the loss of FDX1 and LIAS." (PMID 40969742, 2025). "We demonstrated that PA effectively inhibited cuproptosis in the colonic mucosa of colitis mice, as shown by the reduction in abnormally elevated copper levels in the colonic mucosa, restoration of FDX1, LIAS, and protein lipoylation levels, and decreased DLAT oligomerization." (PMID 40969742, 2025). "In this study, we observed that the transcription and protein expression of FDX1 and LIAS were significantly decreased in the colonic mucosa of patients with active UC with Mayo endoscopic scores ≥2 and in mice with DSS-induced colitis." (PMID 40969742, 2025).
Encephalopathy (2 papers, 2021 to 2022). Encephalopathy is a term that means brain disease, damage, or malfunction. "Previous studies found that mutations in LIAS were associated with non-ketotic hyperglycinaemia-like early-onset convulsions and encephalopathy combined with a defect in mitochondrial energy metabolism, and LIAS overexpression inhibited oxidative stress and inflammation." (PMID 36405901, 2022).
epilepsy (2 papers, 2014 to 2017). A brain disorder characterized by episodes of abnormally increased neuronal discharge resulting in transient episodes of sensory or motor neurological dysfunction, or psychic dysfunction. "Different mutations in LIAS cause severe syndromes characterized by the development of seizures, epilepsy and epileptic encephalopathy." (PMID 28334860, 2017). "Relatively few studies reported on changes in Krebs cycle-related activities, such as pyruvate dehydrogenase and pyruvate kinase in ageing, lipoamide dehydrogenase in Alzheimer's disease, lipoic acid synthetase in epilepsy, and aconitase in Friedreich ataxia." (PMID 24876913, 2014).
gastric cancer (2 papers, 2024 to 2025). A primary or metastatic malignant neoplasm involving the stomach. "Copper death related genes such as LIAS, GLS, and CDKN2A can regulate the function of immune cells, affect the occurrence and development of gastric cancer, and serve as biomarkers for gastric cancer patients." (PMID 41158129, 2025). "We conducted molecular experiments to validate our findings, and the results of Western blot analysis revealed notable disparities in the expression levels of FDX1, LIAS, DLAT, DLST, GCSH, PDHB and PDHA1 in gastric cancer cells between the CSRS‐Low (AGS) and CSRS‐High (HGC‐27) subtypes." (PMID 38898987, 2024).
liver cancer (2 papers, 2023 to 2024). An epithelial or non-epithelial malignant neoplasm that arises from the liver. "In light of this background, it is pertinent to inquire, through bioinformatics and subsequent basic experimental validation, we have learned that in numerous cancer types, including liver cancer, LIPT2, LIPT1, and LIAS, which act as precursors for ALA synthesis, exhibit oncogenic activity." (PMID 39199143, 2024).
non-small cell lung carcinoma (2 papers, 2019 to 2026). A group of at least three distinct histological types of lung cancer, including non-small cell squamous cell carcinoma, adenocarcinoma, and large cell carcinoma. "Dihydrolipoamide acetyltransferase (DLAT) and lipoic acid synthetase (LIAS), two key cuproptosis regulators, are abnormally expressed in non-small cell lung cancer (NSCLC) and are potential biomarkers for clinical diagnosis." (PMID 42222481, 2026).
pancreatic cancer (2 papers, 2022). "In this study, we successfully used cuprotosis-related genes to establish a prognosis-related risk model for pancreatic cancer patients, which included three genes LIPT1, LIAS, and DLAT." (PMID 36117848, 2022). "We selected a normal human pancreatic ductal epithelial cell line (i.e., HPDE6-C7) and 4 pancreatic cancer cell lines (i.e., CFPAC-1, PANC-1, SW1990, and AsPC-1) to examine the expression of DLAT, LIPT1, and LIAS." (PMID 36090999, 2022).
pulmonary fibrosis (2 papers, 2023 to 2025). Chronic progressive interstitial lung disorder characterized by the replacement of the lung tissue by connective tissue, leading to progressive dyspnea, respiratory failure, or right heart failure. "It’s reported that the CRGs, such as FDX1, LIAS, DLD, PDHA1, PDHB, DLAT, and LIPT1, were down-regulated in the lung tissues of pulmonary fibrosis mouse model, and the same results were obtained via analysis of lung tissues scRNA-seq data for human pulmonary fibrosis." (PMID 37266442, 2023).
Sepsis (2 papers, 2024 to 2025). Sepsis is defined as life-threatening organ dysfunction caused by a dysregulated host response to infection. "A bioinformatic analysis of the relationship between the pathogenesis of sepsis and cuproptosis-related genes identified LIAS and PDHB as potential diagnostic biomarkers for cuproptosis-associated sepsis." (PMID 40182687, 2025). "Furthermore, GSE236713 cohort was utilized to verify SLC31A1, MTF1, LIAS and LIPT1 level in sepsis." (PMID 39652607, 2024).
acute myeloid leukemia (1 paper, 2022). Acute myeloid leukemia (AML) is a group of neoplasms arising from precursor cells committed to the myeloid cell-line differentiation. "Conversely, the expression level of LIAS was downregulated in acute myeloid leukemia (LAML), OV, and testicular germ cell tumors (TGCT)." (PMID 35982953, 2022).
acute myocardial infarction (1 paper, 2024). Necrosis of the myocardium, as a result of interruption of the blood supply to the area. "In contrast, patients with acute myocardial infarction exhibit decreased levels of LIAS, PDHB, LIPT1, DLAT, and GLS, along with increased MTF1 levels." (PMID 39360273, 2024).
Adrenocortical carcinoma (1 paper, 2022). "We also discovered that cuproptosis-associated genes including FDX1, LIAS, PDHA1, MTF1, CDKN2A had significant overall survival (p < 0.05), which indicated that cuproptosis-associated genes could be prognosis factors in Adrenocortical carcinoma (ACC)." (PMID 36105090, 2022).
Cerebral ischemia (1 paper, 2024). Restriction of arterial blood supply to the brain associated with insufficient oxygenation to support the metabolic requirements of the tissue. "Eight hub genes (FDX1, LIPT1, LIAS, DLD, PDHA1, DLAT, PDHB, and GLS) were identified as potential core targets of cerebral ischemia." (PMID 39360273, 2024).
cholelithiasis (1 paper, 2025). The presence of crystallized deposits forming in the gallbladder or biliary tree, primarily composed of cholesterol, bilirubin, and bile. "Conversely, the expression of the following genes was positively associated with cholelithiasis risk: LIAS (OR = 1.10, 95% CI = 1.06–1.14), PNKD (OR = 1.12, 95% CI = 1.09–1.15), and SDHA (OR = 1.19, 95% CI = 1.07–1.31)." (PMID 40958306, 2025). "This study, through multi-omics integrative analysis, provides the first evidence of a causal link between mitochondrial-related genes (LIAS, TARS2, HEBP1, PNKD) and cholelithiasis, and evaluates their potential as viable drug targets." (PMID 40958306, 2025). "Through multi-omics integration, we have constructed for the first time a causal pathway linking mitochondrial-related genes, metabolic pathways, and cholelithiasis, providing theoretical support for personalized therapies targeting the genes LIAS, TARS2, HEBP1, and PNKD." (PMID 40958306, 2025). "This study, using the SMR and HEIDI testing methods, investigated the association of genetically predicted mitochondrial-related gene methylation, gene expression, and cholelithiasis, identifying 4 potential drug targets for cholelithiasis: TARS2, LIAS, HEBP1, and PNKD." (PMID 40958306, 2025).
coronary heart disease (1 paper, 2022). "The results showed that six CRGs (LIAS, LIPT1, DLAT, PDHB, MTF1, and GLS) were markedly differentially expressed between stable coronary heart disease (stable_CAD) and AMI." (PMID 36440046, 2022).
dental caries (1 paper, 2025). The decay of a tooth, in which it becomes softened, discolored, and/or porous. "These collective insights position liaS as a promising therapeutic target for disrupting the fungal-bacterial collaborative networks underlying the progression of dental caries." (PMID 40822408, 2025). "This activity ultimately attenuates cariogenicity in vivo, thus highlighting liaS as a pivotal virulence determinant in cross-kingdom infections and emphasizing its potential as a therapeutic target against dental caries." (PMID 40822408, 2025).
diffuse large B-cell lymphoma (1 paper, 2022). "However, a large majority of cuproptosis-associated genes including FDX1, LIAS, LIPT1, DLD, DLAT, and PDHB acted as a low-risk indicator in Lymphoid neoplasm diffuse large B-cell lymphoma (DLBC)." (PMID 36105090, 2022).
mesothelioma (1 paper, 2022). A usually malignant and aggressive neoplasm of the mesothelium which is often associated with exposure to asbestos. "Similarly, cuproptosis-associated genes including LIAS, LIPT1, PDHB, GLS, and CDKN2A had significant overall survival in Mesothelioma (MESO) (p < 0.05)." (PMID 36105090, 2022).
osteosarcoma (1 paper, 2023). A usually aggressive malignant bone-forming mesenchymal neoplasm, predominantly affecting adolescents and young adults. "A study has shown that the cuproptosis-related genes LIAS, PDK1 and BCL2L1 were strongly related to immune cells infiltrating in osteosarcoma, serving as the reliable targets for predicting the patients’ immune response." (PMID 37380924, 2023).